CD4 (CD4 molecule)
Diseases named in the same sentence as CD4 in open-access papers (continued):
Sharing a sentence is not in itself a finding about the gene and the disease.
tumor (continued). "Interestingly, treatment of tumor cells with EGFR tyrosine kinase inhibitors (EGFR-TKI) was shown to upregulate HLA-DR expression on tumor cells and enhance recognition by EGFR875-889-specific CD4 T cells." (PMID 27833557, 2016). "Along with CD8+ and CD4+ T lymphocytes, Th0 subtype of T cells promotes the production of INF-γ and suppresses the secretion of IL-4, contributing to the proliferation of Th1 subtype over Th2 cells in the tumor microenvironment." (PMID 27246873, 2016). "Therefore, we performed IHC and visualized B cells and CD3+, CD4+, and CD8+ T cells in both the primary and secondary tumours." (PMID 27427766, 2016). "To confirm that CD4+ T cell-mediated anti-tumor immunity can be successful in the complete absence of antigen display on the tumor cells themselves, we eliminated MHC II on tumor cells using CRISPR/Cas9." (PMID 27626487, 2016). "However, the effect of in vivo P2Et treatment was partially lost when simultaneous depletion of CD4 and CD8 T cells was done, suggesting that both CD4 and CD8 T cells were important for P2Et anti-tumor activity." (PMID 27253407, 2016). "PD-1, an inhibitory co-signaling molecule regarded as a marker for exhausted, poorly functional CD4+ and CD8+ T cells, often highly expressed in tumor infiltrating T lymphocytes, was also reduced in the peripheral CD4+and CD8+ T cells, suggesting improved immune response." (PMID 27463016, 2016). "The heterogeneous expression of CD4 and CD8 in TL-79 and TL-131 from two double heterozygous mice suggests that these TLs originated from single thymocytes and accumulated subsequent changes during tumor progression." (PMID 27542204, 2016). "Furthermore, inCVAX prompted tumor infiltration of CD3+, CD4+, and CD8+ T cells; but modulated macrophage subsets differently." (PMID 27656328, 2016). "In addition, the AV-SLP conjugates effectively stimulated Th1-type cytokine CD4+ and/or CD8+ T cell-responses in tumor-draining LN-derived T cells." (PMID 27564262, 2016). "As far as OX40 agonists are concerned, they have been shown to enhance proliferation in conventional CD4 and CD8 T cells, and perhaps the proliferation and activity of the non-Treg after anti-OX40 administration overcomes Treg inhibition, leading to tumor destruction." (PMID 27195113, 2016). "In comparison, CD4+ cells were high with or without radiation in the responsive pooled knockout tumours." (PMID 28008921, 2016). "Although 7/17 peptide vaccines elicited robust, mutation-specific CD4 and CD8 T cell responses, the mutation-reactive T cells failed to recognize ID8-G7 tumor cells in vitro." (PMID 27192170, 2016). "CD4+ T cells have been shown to reject tumor cells with no detectable expression of major histocompatibility complex class II (MHC II)." (PMID 27626487, 2016). "Moreover, activated CD4+ T cells aid induction of memory CD8+ T cells, which can maintain long-term tumor control." (PMID 26741508, 2016). "PD-1 blockade also did not significantly enhance the weak CD8 and CD4 responses generated by tumor itself." (PMID 27825115, 2016). "TNFR2 expression was observed for CD4+Foxp3+ Treg and NKp46+ NK cells in all tissues examined, and was additionally observed for tumor-infiltrating CD4+Foxp3− and CD8+ T cells, and for splenic CD11b+Gr1+ myeloid cells from tumor-bearing animals." (PMID 27626702, 2016). "As in non-tumor bearing mice, administration of IL-15SA/IL-15RαSu-Fc to mice induced the greatest effect on NK cells (3.5 fold, p < 0.001), followed by a significant increase in CD8+ and CD4+ T-cells." (PMID 26910920, 2016). "Tumor-infiltrated neutrophils in tumor tissues expressed higher levels of MPO and Fas/FasL, which may be involved in TAN-mediated inhibition of CD4+ and CD8+ T cells." (PMID 27446967, 2016). "Furthermore, the levels of PD-1−TIM-3+ cells decreased in CD4+ and CD8+ T cells in tumor tissues and AEM, as compared to that in patient PBMC." (PMID 27577071, 2016).
tumor (continued). "Interestingly, a positive correlation was observed between the percentages of CD4+DR+, CD8+DR+, CD8+ CD45RO+, CD4+ CD39+, CD8+ CD39+ and CD4+ Treg subsets in the tumor sample and the percentages observed in peripheral blood." (PMID 27689405, 2016). "In MSI colon tumors, CD4+ TIL produces large amounts of IFN-γ, which could then increase the levels of PD-L1 on tumor cells." (PMID 27854240, 2016). "The increased number of CD3+ and CD4+ cells and the CD4/CD8 ratio induced by CIR may be connected with cytokines, which interact with immune cells, enhancing anti-tumor immunity." (PMID 27029063, 2016). "Neither monotherapy with B10G5 or ALT-803 nor combined therapy had a significant impact on total CD4+ T cell numbers in tumor-draining LNs." (PMID 26625316, 2016). "In contrast, reconstitution with CD4+ T cells from either source did not markedly affect tumor growth." (PMID 26981777, 2016). "At time of sacrifice, significant higher CD4+ T cell numbers were detected within the tumor-infiltrating lymphocytes (TILs) and tumor-draining lymph nodes (TDLN) of B16SLC35A1 tumors." (PMID 26741508, 2016). "NKG2D is normally absent in CD4+ T cells but is expressed by a rare population of effector CD4+ T cells in tumor hosts or virally infected individuals." (PMID 26625316, 2016). "Given that whole tumour lysate potentially contains large number of epitopes for CD4+ and CD8+ T-lymphocyte priming, we further investigated whether CD3+ tumour-specific IFNγ-secreting lymphocytes were being elicited by antigen loaded-DCs by flow cytometry." (PMID 26795765, 2016). "Moreover, in vivo treatment of tumor-bearing mice with withaferin-A decreased tumor weight, reduced the number of granulocytic MDSC, and blocked MDSC-mediated suppression CD4+ and CD8+ T cells activation." (PMID 26959007, 2016). "This is remarkable, since CD4+ T-cell depletion lowers tumour growth in non-vaccinated mice, indicating that cDC2 vaccination switches the CD4+ T-cell pool from mainly pro-tumoral to mainly anti-tumoral." (PMID 28008905, 2016). "CD4 depletion alone or in combination with subsequent radiation therapy did not affect tumor growth." (PMID 27281029, 2016). "All mice adoptively transferred with CD4+ T cells showed highly significant control of tumor growth compared with controls that received no cells." (PMID 27121060, 2016). "However, tumour tissues from Taxol or PTX/PEG2k-Fmoc-NLG(L) groups had lower percentages of T cells including Treg, CD4+ and CD8+ T cells, but higher percentage of MDSC than the group treated with PEG2k-Fmoc-NLG(L) alone." (PMID 27819653, 2016). "CD4+ T lymphocytes (also known as helper T lymphocytes) recognize antigens presented by MHC class II molecules, assist cytotoxic CD8+ T cells, and aid antibody production by B lymphocytes, thereby increasing the efficiency of tumor destruction." (PMID 27368058, 2016). "All studied T cell subsets (CD3, CD4, and CD8) peaked in numbers at day 17 after tumor inoculation." (PMID 27610392, 2016). "Taken together, these results suggest that the strong antitumor effect elicited by RdB/IL12/shVEGF is associated with markedly enhanced infiltration and activation of CD4+ T, CD8+ T, DC, and NK cells to tumor tissue and concurrent inhibition of immunosuppressive Treg accumulation." (PMID 27821803, 2016). "The outgrowth of tumor-specific T cells of only a CD4+ phenotype should not pose a problem for their use in ACT." (PMID 27619514, 2016). "Therefore, polyclonal antigen-specific CD4+ and CD8+ T cells are directly induced by DC-tumor FCs in the draining lymph node." (PMID 27240347, 2016). "Of note, CD4+ depletion in control mice did not alter the rate of tumor progression relative to non-depleted control mice (data not shown)." (PMID 27190629, 2016). "Notably, both CD4+ and CD8+ OVA-specific T cells primed by desialylated OVA-pulsed DCs, exhibited higher cytotoxic activity towards OVA-expressing tumor cells, when compared to those primed with fully sialylated OVA-pulsed sDCs." (PMID 27203391, 2016).
tumor (continued). "Our results revealed that treatment with CTLA-4 blockade augmented the number of ICOS+ CD4+ T cells but not ICOS+ CD8+ T cells in the tumor, blood, and spleen." (PMID 26961085, 2016). "PD‐1 expression levels were measured from patient tumor microenvironment by immunohistochemistry and the results indicated that PD‐1 expression on peripheral CD4+ cells does not reflect PD‐1 expression on cells in the tumor microenvironment." (PMID 27709793, 2016). "LAG-3 expression in CD4+2D2-IEL-THIGH cells from the gut was minimal, but its intracellular expression was markedly higher in the CNS-CD4+2D2-IEL-THIGH cells, similar to what was previously reported in tumour-infiltrating CD8+ T cells." (PMID 27198196, 2016). "Alternative immune approaches include utilizing tumor-associated antigens (TAAs) that stimulate cellular or humoral responses and can efficiently eliminate tumor cells in some cases, since peptides derived from TAAs can be presented with MHC class I/II by CD8+/CD4+ T cells, respectively." (PMID 27446916, 2016). "While early cognate interactions with tumor-specific B cells reduced the number of CD4+ T cells, the total number of iTreg cells was independent of the number of CD4+ T cells and B cells and was not predictive of survival." (PMID 27121060, 2016). "Results demonstrated that IL-13 could be expressed by CD3, CD4, CD8, CD56, CD68 and CD20 positive cell respectively in ESCC tumor tissue." (PMID 26771842, 2016). "An advantage of using endogenous MUC1 CD4+ and CD8+ epitopes was that the T cells generated could be re-stimulated at the site of the tumor by endogenous MUC1 peptides for cytokine production and CTL activity." (PMID 27472370, 2016). "However, Mo-DCs sorted from LLC-OVA tumours were inefficient inducers of naive OVA-specific CD8+ and CD4+ T-cell proliferation." (PMID 28008905, 2016). "In addition to inducing tumor apoptosis, TCP-1/TNFα or TCP-1/IFNγ also increased the infiltration of CD8+ and CD4+ T cell in the tumor leading to enhanced antitumor immunity." (PMID 27342639, 2016). "It was illustrated that miR-155 accelerated the accumulation of functional MDSCs in the tumor microenvironment by suppressor of cytokine signaling (SOCS) 1 repression and reduced ability to license the generation of CD4+Foxp3+ regulatory T cells (Tregs), thereby facilitating tumor growth." (PMID 27458169, 2016). "Tumor cells also failed to support proliferation of Id-specific CD4+ T cells in the presence of synthetic Id peptide (data not shown)." (PMID 27626487, 2016). "Moreover, there are evidences in literature that tumor growth inhibition induced by dsRNA or poly(I:C) critically depends on the production of type I IFNs and is accompanied by elevation of tumor-specific CD8(+) and CD4(+) T cell number." (PMID 26981617, 2016). "ACT with 5 × 106 CD4+ Th cells alone moderately delayed tumor growth, but no tumor-free survival was observed." (PMID 27588200, 2016). "Besides the tumor related symptoms (irritable cough, chest distress, and hemoptysis), NSCLC downregulates the CD4/CD8 ratio in patients' peripheral blood and weakens the immune system." (PMID 27800005, 2016). "We then analyzed Tim‐3 on peripheral CD4+ and CD8+ T cells in patients with different tumor stages." (PMID 27516959, 2016). "Twenty days later, tumours and peripheral lymph nodes were excised and labelled with antibodies to surface markers to detect the phenotype of the immune cell infiltrate, including CD3+, CD4+ and CD8+ T cells, B cells, macrophages and dendritic cells." (PMID 27756214, 2016). "While CD4+ T cells were adoptively transferred simultaneously as the CD8+ T cells, the simulations incorporated just ACT of CD8+ T cells, as a slight inhibition of tumor growth was dependent on CD8+ T cells." (PMID 28101055, 2016). "Also, the presence of infiltrating CD4+, CD8+, and FOXP3+ cells in tumor samples was assessed by immunohistochemistry." (PMID 27463005, 2016).
tumor (continued). "Strikingly, single depletions of CD4 or CD8 T cells did not significantly affect the P2Et anti-tumor effect." (PMID 27253407, 2016). "Poor Th1 response may be explained by T cell inhibition, either by T-cell tolerance to tumor antigens (PD-1 and CTLA-4 pathways) or increased pro-apoptosis of CD4+ T cells (Fas pathway)." (PMID 27766079, 2016). "Even enhanced suppressive activity towards CD4+ T cells became evident in splenic MO-MDSC from tumor-bearing CSC mice which had not been seen directly after cessation of CSC." (PMID 27391954, 2016). "Total CD4+ T cells in the spleens of mice with active tumor growth were not significantly different than those in mice with dormant BCL1 tumor or no tumor." (PMID 27959896, 2016). "Recent research reveals the development of DC-based anti-tumor immunotherapy, which is driven by the strong interaction between DCs and T cells, whereby DCs present tumor antigens via MHC I and MHC II and thus activate tumor-specific- CD8+ and CD4+ T cells." (PMID 26891999, 2016). "It is clear that TILs are heterogeneous and contain various immune cell subsets, including innate cells (e.g., NK cells and macrophage) and adaptive immune cells (e.g., CD4+ T cells, CD8+ T cells, and regulatory T cells (Tregs)), which can suppress or promote the progression of tumours." (PMID 27725696, 2016). "The availability of CD4+ and CD8+ knockout chicken will provide valuable tools to study the role of these cells in vaccine-induced protective immunity against viral replication and tumour growth." (PMID 27894330, 2016). "Meanwhile, 125I implantation also could excite the anti-tumor immune response in HCC patients by adding CD3+ and CD4+ immunocytes and facilitating Th2/Th1 deviation." (PMID 27958384, 2016). "A similar phenomenon has previously been described in the adoptive transfer experiments of SMARTA CD4 Tg lines and CD8 Tg lines specific for the P1A tumor antigen which fail to generate memory cells under certain conditions despite displaying early effector function." (PMID 26752171, 2016). "Eleven patients with the PD‐1 expression in tumor microenvironment were negative, whereas the median percentage of PD‐1 expression on the surface of peripheral blood CD4+ T cells was 13.5% (range: 3.9–34.55%) and the median MFI was 640 (range: 182–1377)." (PMID 27709793, 2016). "Compared with CD4+ T cell help, anti-CD40 induced an even stronger bias towards IgG2a/c, and protected against lung metastases after i.v. administration of B16.mHELMCC tumor cells." (PMID 27121060, 2016). "Significant differences in the localization pattern of immune cell density between the four tumor regions were confirmed for CD3+ (p = 0.002), CD4+ (p = 0.015), CD8+ (p = 0.006), CD20+ (p = 0.007), CD25+ (p = 0.008) and CD68+ (p = 0.010) cells by Friedman two-way ANOVAs." (PMID 27221038, 2016). "We demonstrate that the enhanced antitumor effect was associated with increased IFN-γ expression, induction of a tumor-specific immune response, recruitment of immune cells (CD4+, CD8+ T cells, DCs, and NK cells), and efficient prevention of tumor-induced thymic atrophy." (PMID 27821803, 2016). "CD4+ T cells have been reported to also kill MHC II negative tumor cells via indirect activation of tumor-residing macrophages and NK cells." (PMID 27843441, 2016). "In addition, treatment with a combination of ascophyllan and ovalbumin (OVA) in the tumor-bearing mice promoted proliferation of OVA-specific CD4 and CD8 T cells and migration of those cells into the tumor, consequently inhibiting the tumor growth." (PMID 27008707, 2016). "If CD4+ T-cells were depleted in a therapeutic study, one would not know if the effect was due to lack of CD4+ anti-tumor effector response or due to lack of CD4+ T-cell help in the activation of a vaccine-specific CD8+ T-cell response." (PMID 28018602, 2016).
tumor (continued). "Higher frequencies of CD4+ T and CD8+ T cells were observed in the tumors treated with RdB/IL12/shVEGF in comparison to RdB-, RdB/shVEGF-, or RdB/IL12-treated tumor tissues, indicating that RdB/IL12/shVEGF induced the strongest activation and recruitment of T cells to the tumor tissues." (PMID 27821803, 2016). "Similar to results observed with the wild-type mice, the protective anti-tumor effects induced by E6E7 vaccination were not affected by the absence of CD4+ T-cells." (PMID 26390407, 2015). "Although we did not observe a difference in CD8+ and CD4+ T infiltrating lymphocytes, we found a significant increase in the number of Tregs in B16-W6_pSIL10 tumours with respect to control." (PMID 26101462, 2015). "Injection of anti-CD4 antibody, gemcitabine and DCs did not inhibit tumor growth, but injection of anti-CD8 antibody greatly reduced tumor sizes." (PMID 26181041, 2015). "The percentage of CD4+, CD8+ cells was comparable in the tumor samples within all four treatments." (PMID 26181041, 2015). "Unlike non-tumor bearing mice, 4T1-bearing mice displayed increased splenic percentages of CD4+ and CD8+ T cells, in addition to the increased percentages of effector and central CD8+ T cells." (PMID 26317648, 2015). "We also observed that similar to human BCCs, the tumor stroma of murine BCCs show characteristic features of a Th2 microenvironment including increased expression of IL4 and the presence of cells expressing CD4/FOXP3." (PMID 26413810, 2015). "Another tumor antigen, gp100, is a melanosomal antigen that has been reported to access the endogenous MHC class II pathway and present efficiently to gp-100-specific CD4+ T cells." (PMID 26441969, 2015). "Exposure to tumor cells did not interfere with the ability of iMoDCs to stimulate CD4+ or CD8+ T cell proliferation." (PMID 25886502, 2015). "Furthermore, dasatinib-treated CML patients have a higher proportion of effector CD4+ T cells that differentiate into Th1-type cytokine producers and are capable of producing IFN-γ, which is key for tumor control." (PMID 25709607, 2015). "As observed in the prophylactic assay, the vaccination of CD4+ T-cells knockout mice did not reduce the anti-tumor effects." (PMID 26390407, 2015). "CD4+ CD25lo Tconvs were sorted from lymphoid tissue and co-cultured in the presence of anti-CD3 and anti-CD28 beads with either CD69+ or CD69− Tregs sorted from tumor draining or non tumor draining lymph nodes, at varying Tconv : Treg ratios." (PMID 26433463, 2015). "Depletion of the CD4+ population showed no impact on E0771 tumor growth in both WT and KO mice as compared to non-depleted groups." (PMID 25760243, 2015). "As is known, lymphocytes can reduce malignant progression as tumor infiltration via a series of subtypes of lymphocytes, CD3+ T cells, CD8+ T cells, Th1 CD4+ T cell, and p46+ natural killer cells, which has been shown to improve the survival of patients with malignancy." (PMID 26137435, 2015). "Furthermore, an increase in potentially anti-tumorigenic IFNγ producing CD4+ and CD8+ T cells also indicate improved anti-tumor immunity." (PMID 26061815, 2015). "We propose a scenario in which, when an oncogene such as p48 affects the normal gene expression and induces tumor progression, the increment of MHC II surface molecules can be considered a strategy used by cells to activate a tumor-specific immune response of CD4+ T cells." (PMID 26081906, 2015). "We also examined the requirement of donor CD4+ T-cell-derived IFN-γ for promoting the response of tumour-specific CD8+ T cells." (PMID 25850032, 2015). "Gradually increased cell proportions and absolute numbers of tumor-infiltrating CD4+ and CD8+ T cells were observed in both 4T1 and E0771 tumor-bearing mice with the increasing tumor size and progression, indicating accumulation of both CD4+ and CD8+ T cells into tumor sites." (PMID 25968569, 2015).